USP44 (ubiquitin specific peptidase 44)
Diseases named in the same sentence as USP44 in open-access papers (continued):
Sharing a sentence is not in itself a finding about the gene and the disease.
tumor (33 papers, 2015 to 2025). "The expression of USP44 is diminished in HCC tissues, and clinical pathological analysis further indicates that low levels of USP44 expression are associated with poorer prognosis and advanced tumor stages in HCC patients." (PMID 40607251, 2025). "In contrast, USP44 acts as a tumor suppressor, with its deficiency linked to spontaneous lung tumor development in mouse models, underscoring its protective role against tumorigenesis." (PMID 40136480, 2025). "A recent study suggested that low USP44 expression is associated with poorer survival and a later tumor stage in HCC." (PMID 38097536, 2023). "Taken together, our findings show that low expression of USP44 indicates a poor prognosis and is associated with tumour relapse in NPC patients." (PMID 35079021, 2022). "USP44 is a deubiquitinase that functions as a key regulator of mitotic spindle checkpoint and loss of Usp44 in mice resulted in spontaneous tumor development, especially in lung." (PMID 29088828, 2017). "Low expression of USP44 is associated with tumour relapse and a poor prognosis in NPC patients." (PMID 35079021, 2022). "Moreover, we revealed that reduced expression of USP44 indicates a poor prognosis and is associated with tumour relapse in NPC patients." (PMID 35079021, 2022). "It is easy to appreciate how the loss of USP44, resulting in both increased mutagenesis and increased chromosome missegregation, may therefore act as a powerful tumor suppressor." (PMID 33937266, 2021). "In contrast, in pancreatic cancer, thyroid cancer, colorectal cancer, and liver cancer, USP44 inhibits tumor progression." (PMID 40607251, 2025). "We found that the role of USP44 as a tumor suppressor is, in part, dependent on its binding to the centriole protein centrin—a complex that is required for proper timing of centrosome separation and DNA repair through the nucleotide excision repair pathway." (PMID 39767807, 2024). "When using an FDR significance threshold of < 0.01, USP44 was also significantly down-regulated in tumour samples." (PMID 39095452, 2024). "USP44-overexpressing 8505C cell-derived xenograft tumors showed significantly slower growth and reduced tumor burden in contrast to the control group." (PMID 39430240, 2024). "Meanwhile, we analyzed USP44 mRNA expression and methylation levels, and investigated their relationship in other 10 tumor types using the TCGA database." (PMID 39430240, 2024). "Background/Objectives: The enzyme ubiquitin-specific protease 44 (USP44) is a deubiquitinating enzyme with identified physiological roles as a tumor suppressor and an oncogene." (PMID 39767807, 2024). "Due to its importance in DNA damage repair and transcription, and its general importance as a tumor suppressor gene, we sought to validate the interaction between USP44 and BRCA2." (PMID 39767807, 2024). "USP44-overexpressing tumor tissues exhibited a higher expression of USP44, while the percentage of Ki-67-positive cells showed a marked decrease compared to control tumor." (PMID 39430240, 2024). "On the contrary, USP44-knockdown 8505C cell-derived xenograft tumors displayed accelerated growth, with a remarked increase in both tumor volume and weight." (PMID 39430240, 2024). "We examined the effect of a nuclear-residing Gli1 mutant on USP44 overexpression-mediated tumor inhibition." (PMID 38097536, 2023). "The tumor suppressive function of USP44 was evaluated in a series of in vitro and in vivo experiments." (PMID 38097536, 2023). "Next, we demonstrated that USP44 knockout in murine hepatocytes impaired the tumor suppressive function of USP44 in a mouse model of diethylnitrosamine (DEN)/carbon tetrachloride (CCl4)-induced hepatocarcinogenesis." (PMID 38097536, 2023). "In contrast, USP44 overexpression reduced the proliferation and migration ability of tumor cells in HCC." (PMID 37204480, 2023).
tumor (continued). "We confirmed that USP44 deletion significantly promoted the proliferation of tumor cells through immunofluorescence of proliferating cell nuclear antigen (PCNA) in tumor samples." (PMID 38097536, 2023). "The mean methylation of CpGs in two genes is hypomethylated in normal and hypermethylated at the terminal tumor regions (USP44 and SATB2); the opposite is true for three other genes (KRBA1, ANKS4B, and KDM8)." (PMID 37120552, 2023). "Next, we sought to verify that the Hh signaling pathway was involved in the modulatory effect of USP44 on tumor growth and metastasis in vivo." (PMID 38097536, 2023). "To summarize, our results highlight, for the first time, the tumor-suppression role of USP44 in HCC and suggest a new prognostic biomarker in this disease." (PMID 37204480, 2023). "To demonstrate the tumor suppressive role of USP44 in HCC, we further performed in vitro and in vivo experiments." (PMID 38097536, 2023). "USP44 has been reported to act as a tumour suppressor that regulates cell cycle arrest and DSB responses by modulating H2B mono-ubiquitylation." (PMID 35079021, 2022). "The protein levels of TRIM25 and caspase 3, a cell apoptosis-related protein, were increased, and the levels of Ku80 were decreased in the tumours of the USP44 group compared with those of the control group." (PMID 35079021, 2022). "Compared with the control group, the USP44 group exhibited reduced xenograft growth in terms of the size, volume, and weight of the excised tumours, especially after IR, indicating that the tumours in the USP44 group were much more sensitive to IR." (PMID 35079021, 2022). "We combined these results with the clinical data and found that locoregional recurrence was evidently related to weak USP44 staining in tumour samples." (PMID 35079021, 2022). "The introduction of the ectopic EZH2 rescues the suppression of tumor activity after the USP44 knockout." (PMID 35924159, 2022). "Clinically, low expression of USP44 indicates a poor prognosis and facilitates tumour relapse in NPC patients." (PMID 35079021, 2022). "Apart from USP22, USP44 has been shown to be upregulated in CSCs of breast cancer and promote tumor angiogenesis." (PMID 35924159, 2022). "We previously reported the tumor prone phenotype of Usp44 null mice in the context of its role in the protection against aneuploidy." (PMID 33937266, 2021). "Results showed that USP44 was a hypermethylation gene in the tumor group, and the most related methylation positions were cg22538054, cg23982858, cg22802813, and cg17368254." (PMID 32633782, 2020). "USP44 is known to play important roles in the cell cycle, tumor progression, and embryonic stem cell differentiation." (PMID 32644293, 2020). "Some studies have suggested that USP44 overexpression promotes tumor development, whereas other studies have indicated that USP44 inhibits proliferation of tumor cells." (PMID 32164618, 2020). "We explored the role of USP44 as a tumor marker based on information from the TCGA Data Portal and GEO 102010 database." (PMID 32164618, 2020). "We demonstrated that USP44 overexpression inhibited migration of tumor cells through wound-healing and cell-migration experiments." (PMID 32164618, 2020). "USP44 function in the proliferation and migration of tumor cells was assessed by cellular and molecular analyses using ccRCC lines (786-O cells and Caki-1 cells)." (PMID 32164618, 2020). "Results showed that USP44 had low expression in tumor tissues and correlated with the pathologic stage and grade of tumors." (PMID 32164618, 2020). "Several of these genes (including MGMT, RAD17, and USP44) show prior evidence of a tumour suppressive function." (PMID 29089486, 2017). "It will be important to determine which of the functions of USP44 are critically required for tumor suppression." (PMID 26442100, 2015). "Furthermore, the positive correlation between GOLPH3 and USP44 in tumor samples also decreases substantially." (PMID 40136480, 2025).
tumor (continued). "Additionally, we demonstrate that USP44 functions as a tumor suppressor by a series of in vitro functional experiments as well as xenograft and transgenic mouse models." (PMID 39430240, 2024). "We also assessed the tumor-suppressive effect of USP44 using xenograft tumor models." (PMID 39430240, 2024). "Consistently, we found that USP44 upregulation effectively inhibited tumor growth in mice." (PMID 38097536, 2023). "Furthermore, we found that patients with low USP44 expression were prone to larger tumor size, distant metastasis, and late-stage disease." (PMID 38097536, 2023). "Correlation between tumor USP44 expression and clinicopathologic features." (PMID 37204480, 2023). "In addition, USP44 overexpression inhibited the growth of the tumors whereas the downregulation of Itch blunted the decline in tumor growth." (PMID 38097536, 2023). "Collectively, these results suggest the tumor suppressive role of USP44 in HCC." (PMID 38097536, 2023). "Herein, we revealed that USP44 may exhibit a tumor suppressive role in HCC progression through inhibiting the Hh pathway." (PMID 38097536, 2023). "Above all, our data suggest that USP44 may have a tumor suppressive role in HCC and has the potential to serve as a diagnostic biomarker for HCC." (PMID 38097536, 2023). "Clinicopathologic analysis further showed that low USP44 expression correlated with poorer survival and a later tumor stage in HCC, suggesting that USP44 could be a predictor of poor prognosis in patients with HCC." (PMID 37204480, 2023). "In addition, the upregulation of USP44 delayed tumor growth and lung metastasis while the introduction of mutant Gli1 attenuated the suppression of tumor growth and metastasis mediated by USP44 overexpression." (PMID 38097536, 2023). "Here we now demonstrate a second distinct tumor suppressive function of USP44." (PMID 33937266, 2021). "We attempted to verify the role of USP44 in tumor cells by silencing USP44 expression with shRNAs." (PMID 32164618, 2020). "Rescue experiments showed that silencing USP44 expression to promote the proliferation and migration of tumor cells could be blocked by a JNK inhibitor." (PMID 32164618, 2020). "Accordingly, the function of USP44 in neoplasms is tumor‐dependent." (PMID 32285989, 2020). "Because the two types of tumor cells we used have different migration abilities, USP44 overexpression slowed down the migration ability of 786-O cells at the early stage (2 h, 3 h), and slowed down the migration ability of Caki-1 cells at the late stage (10 h, 24 h)." (PMID 32164618, 2020). "The poor tumor growth and robust anti‐tumor immune mobilization seen in Usp44fl/fl Foxp3Cre+ mice illustrate how FOXP3‐stabilizing DUBs like USP44 may be tempting molecular targets for such future therapy." (PMID 32644293, 2020). "USP44 expression was negatively correlated with tumor stage, tumor grade, and patient survival." (PMID 32164618, 2020). "However, in the aneuploidy group, tumor invasion was significantly deeper (P < 0.01) and distant metastasis rate tended to be higher in the high USP44 expression group." (PMID 28544703, 2017). "USP44, belonging to the USP family, is implicated in regulating various physiological functions and pathological processes, including cell cycle regulation, chromosome segregation, immune response, stem cell differentiation, DNA damage response and tumor progression 8, 10, 11, 38-41." (PMID 39430240, 2024). "Notably, Usp44 knockout animals exhibited an increased incidence of spontaneously arising tumors due to heightened chromosome segregation errors, further supporting its tumor-suppressing function." (PMID 39430240, 2024). "To explore the role of USP44 in HCC growth in vivo, we established a subcutaneous tumor model and a liver orthotopic xenograft tumor model in mice." (PMID 38097536, 2023). "Targeting USP44 can reduce FOXP3 expression at the protein level, and thus break immune tolerance in tumor patients." (PMID 37053008, 2023).
tumor (continued). "USP19, USP44, USP46, and USP53 has been revealed as potential tumor suppressor in KIRC in the previous study." (PMID 37259026, 2023). "Interestingly, the function of USP44 in tumorigenesis could be tumor-dependent." (PMID 36483601, 2022). "Our findings uncover an uncovered mechanism by which USP44 regulates the cell cycle and DSB response to induce a tumour suppressor effect in NPC." (PMID 35079021, 2022). "While mechanistic details remain, our data provide compelling evidence that USP44 stabilizes DDB2 and that this mechanism is crucial for efficient XPC recruitment and has physiological relevant roles in tumor prevention." (PMID 33937266, 2021). "In basal-like TNBCs, there is an inverse relationship between USP44 and RNF20/RNF40 with USP44 being more highly expressed, concomitant with lower levels of H2Bub1 in these tumours." (PMID 33233707, 2020). "To explore how USP44 regulates the proliferation and migration of tumor cells, we measured the activation of AKT, JNK, p38, and ERK signal pathways in USP44-overexpression and control groups." (PMID 32164618, 2020). "Our proposed tumour suppressors include genes previously suggested to play a role in oncogenesis (e.g., MGMT and USP44), as well as novel candidates (e.g., KIAA1551, CASP3, and MAFTRR)." (PMID 29089486, 2017). "I will next focus on USP44 and BAP1, which have been best characterized as tumor suppressors in human pathology." (PMID 26442100, 2015). "Recovering the expression of the tumor suppressor, such as USP19, USP44, and USP53, also might reach the tumor-inhibited effect for this type of patient." (PMID 37259026, 2023). "The results showed that expression of USP44 was lower in advanced-stage (stages IV) than in early-stage (stages II and III) HCC tumors (p = 0.049), suggesting that USP44 expression is related to tumor staging." (PMID 37204480, 2023). "To determine whether USP44 promotes the radiosensitivity of NPC cells in vivo, we generated subcutaneous tumour xenograft models." (PMID 35079021, 2022). "Respectively, the expression of CDO1, CELF2, ITPRIPL1, KCNH8, RIC3, USP44 and ZSCAN23 was significantly lower in tumor tissues, whereas the expression of PTK6 and RAB25 was significantly higher in tumor tissues." (PMID 34056873, 2021). "CD8+ T cells from tumor‐bearing mice lacking USP44 also were found to express markedly higher levels of TNFα and significantly higher levels of the effector molecule granzyme B than their wild‐type counterparts." (PMID 32644293, 2020). "While this ubiquitin‐specific protease is known to be important in the cell cycle and tumor biology, no such role for USP44 in Tregs or immune regulation had been uncovered." (PMID 32644293, 2020). "Liu et.al revealed that USP44+ CSCs subclones with an ALDH1+/USP44+/IL6+/IL8+ phenotype may promote VM and tumor aggressiveness." (PMID 31772665, 2019). "USP44 acts as a tumor suppressor by preventing chromosome segregation errors via deubiquitylation of the anaphase promoting complex (APC) coactivator Cdc20, and USP44 deletion leads to spontaneous tumor formation, preferentially in the lungs." (PMID 27516771, 2016). "However, whether USP44, E2FS, and EML6 may play a role in regulating tumor-immune interaction remains to be determined." (PMID 34267181, 2021). "In line with this notion, analysis of FOXP3+ CD4+ T cell frequencies across the tissues of MC38 tumor‐bearing wild‐type and Usp44fl/flFoxp3Cre+ mice revealed marked reductions in the relative size of the Treg pool when USP44 expression was lacking in these cells." (PMID 32644293, 2020). "Similarly, the negative correlation between OSM and USP44 in tumor samples is notably reduced." (PMID 40136480, 2025).
USP44 also shares sentences with these, for which no sentence is quoted: acute lymphoblastic leukemia (2 papers); congenital heart disease (2); hepatocellular carcinoma (2); glioblastoma (1); Insulin resistance (1); liver cancer (1); lung adenoma (1); melanoma (1); nasopharyngeal tumors (1); pancreatic ductal adenocarcinoma (1); renal carcinoma (1); testicular cancer (1); thymoma (1); type 2 diabetes (1).